MYCN (MYCN proto-oncogene, bHLH transcription factor)
Diseases named in the same sentence as MYCN in open-access papers (continued):
Sharing a sentence is not in itself a finding about the gene and the disease.
neuroblastoma (continued). "Gene expression of MYCN-amplified and non-amplified stage 4 (metastatic) neuroblastoma tumors and cell lines was assessed using TLDA assays." (PMID 23982484, 2013). "Our in vitro data suggests that BET inhibition triggers a potent cytotoxic response in neuroblastoma cell lines irrespective of MYCN copy number." (PMID 24009722, 2013). "In addition, age and MYCN amplification (MNA) status were retrieved for 112 unfavorable neuroblastomas of the Swedish Childhood Cancer Registry, representing a 25-year neuroblastoma cohort of Sweden, here used for validation of the findings." (PMID 23656755, 2013). "Similarly, in neuroblastoma models BET inhibitors down-regulate MYCN expression and the regulation of cellular growth by BET is partially MYCN-dependent." (PMID 24293458, 2013). "To examine the therapeutic potential of I-BET726 in vivo, we established subcutaneous xenograft models of non-MYCN-amplified and MYCN-amplified neuroblastoma in immunocompromised mice using the SK–N-AS and CHP-212 cell lines, respectively." (PMID 24009722, 2013). "The oncogene, MYCN, is the most significant negative prognostic factor for neuroblastoma survival, and neuroblastoma tumors with MYCN amplification are more likely to be metastatic and to recur." (PMID 24130898, 2013). "Hence, with the support of these previously published data, it seems that our case harboring chromosome 11 and 12 amplifications is not totally unique and implies that such and other non-MYCN amplifications may underlie a minor subset of aggressive neuroblastomas." (PMID 23656755, 2013). "In multivariate analyses, the TAC haplotype was not an independent predictor of outcome in this subgroup of neuroblastomas, after adjusting for age at diagnosis, clinical stage and MYCN amplification status." (PMID 23533647, 2013). "Despite limitations in the literature, most data suggest that it is characterized by a more aggressive clinical course and an overall worse outcome compared to neuroblastoma in children while MYCN is not usually amplified." (PMID 24396620, 2013). "Unfortunately, however, efficacious and immediately translatable methods to deplete MYCN directly into a neuroblastoma patient are not yet available." (PMID 23091802, 2012). "Finally, miR-9 activated by MYC/MYCN mediated E-cadherin down-regulation resulting in the activation of β-catenin, and VEGF, and metastases in human cancers, including neuroblastomas and breast tumors." (PMID 22752005, 2012). "In this study, we found that a specific NF-κB inhibitor, NSC 676914, synergized growth inhibition mediated by topotecan in both MYCN and non-MYCN amplified neuroblastoma cell lines." (PMID 22436457, 2012). "We found that neuroblastoma cells with amplification of MYCN are more sensitive than MYCN negative cells to camptothecin and topotecan killing." (PMID 22619121, 2012). "This region includes both MYCN and ALK, two well characterized oncogenes in neuroblastoma." (PMID 22788920, 2012). "MYCN is part of a large family of oncogenes found to be amplified in human neuroblastomas and is correlated with aggressiveness and a negative prognosis in this type of pediatric cancer." (PMID 22253826, 2012). "MDM2 is a direct target gene of MYCN and non-syntenic co-amplification of MDM2 and MYCN has been reported in neuroblastoma." (PMID 23226679, 2012). "Since polyamine inhibition appears to be clinically well tolerated, these approaches, particularly when combined with chemotherapy, have great potential for improving neuroblastoma outcome in both MYCN amplified and non-MYCN amplified neuroblastomas." (PMID 23181218, 2012).
neuroblastoma (continued). "We tested these combinations in SK-N-AS and two additional neuroblastoma cell lines NB-1691 (MYCN amplified) and SH-SY5Y (MYCN non-amplified) to ensure that the synergistic effect was not specific to any cell line." (PMID 22436457, 2012). "As MYCN itself is a direct activator of the mir-17-92 cluster, we assume that the MYCN-targeting function of mir-19a/-b is disturbed in MNA neuroblastoma cells." (PMID 21654684, 2011). "Recently, a group has reported the association of miR-542-5p overexpression in favorable histology, MYCN nonamplified neuroblastoma samples." (PMID 21789031, 2011). "Here, we show that mutations in the MYCN 3′UTR are rare, both in MNA and non-MNA neuroblastoma cells." (PMID 21654684, 2011). "To confirm that transcriptional suppression of MKP3 was directly mediated by N-Myc, we transfected a Luciferase reporter construct carrying MKP3 gene promoter into TET21/N cells, a human neuroblastoma cell line carrying a MYCN transgene under the control of a TET-OFF promoter." (PMID 21698133, 2011). "One interesting study demonstrated that neuroblastomas have increased levels of miR-17-5p, which inhibits p21 and BCL2L11 (a.k.a., BIM) expression, and that p21 downregulation is significant in tumors with MYCN amplification and a poor clinical outcome." (PMID 24212967, 2011). "Conversely, in neuroblastoma caspase-8 gene methylation correlated with amplification of the MYCN gene, whereas caspase-8 protein was absent in the majority of tumors irrespective of MYCN amplification." (PMID 24281211, 2010). "Analysis for sporadic neuroblastoma cases also showed that the MK level was also remarkably higher than in non-tumor controls, and correlated with the statuses of MYCN amplification and stage." (PMID 24281085, 2010). "The five genes identified as candidate genes involved in neuroblastoma progression were: MYCN (neuroblastoma derived), NPW (neuropeptide W), SLC30A3 (solute carrier family 30, member 3), MYCNOS (neuroblastome derived opposite strand), and MYCN* (v-myc myelocytomatosis viral related oncogene)." (PMID 20380745, 2010). "A 55-gene signature derived from the expression profile of metastatic neuroblastoma lacking MYCN amplification provided a new definition of high and low risk of disease progression." (PMID 20624283, 2010). "Expression of the B-MYB transcription factor has been previously shown to be a poor prognostic indicator in neuroblastoma, independent of MYCN amplification." (PMID 21304174, 2010). "Unfortunately, the main genetic alteration, MYCN amplification, does not explain the poor outcome of all neuroblastoma patients, suggesting that additional biomarkers of disease progression are still needed." (PMID 20444257, 2010). "At the present time, the prognostic significance of heterogeneously MYCN amplified neuroblastomas is not known, but amplification of a substantial number of tumour cells in a specimen is still considered an ominous sign." (PMID 19401703, 2009). "NTRK1 c.1810C>T polymorphism appears to be a new independent prognostic factor of poor outcome in neuroblastoma, especially in children under 18 months of age with no MYCN amplification." (PMID 20003389, 2009). "To further analyze MYCN/c-MYC activity as well as differential regulation of MYCN/c-MYC target genes in neuroblastoma subtypes, we thought to define a comprehensive set of target genes directly regulated by MYCN and/or c-MYC in neuroblastoma cells." (PMID 18851746, 2008). "Spontaneous regression is most frequently observed in a subset of disseminated MYCN single-copy neuroblastomas (non-amplified (NA)), termed stage 4s (stage 4s-NA)." (PMID 18851746, 2008). "These cells showed an increased expression of the cluster (data not shown), similar to that observed in MYCN-amplified neuroblastoma cells." (PMID 18493594, 2008). "Neuroblastoma-derived cell lines that lack amplified MYCN generally express c-MYC rather than MYCN, often at higher levels than normal tissues." (PMID 18851746, 2008).
neuroblastoma (continued). "A defined set of MYCN/c-MYC target genes was induced in stage 4-non-amplified but not in stage 4s-non-amplified neuroblastomas." (PMID 18851746, 2008). "Direct regulation of these target genes by MYCN/c-MYC was assessed by analyzing the binding of MYCN and c-MYC protein to target gene promoters using PCR- and array-based chromatin immunoprecipitation (ChIP and ChIP-chip, respectively) in different neuroblastoma cell lines." (PMID 18851746, 2008). "We found here that in these three neuroblastoma cell lines elevated MYCN expression levels did not correlate with up-regulation of the Warburg effect or a concomitant reduction in cellular reliance on mitochondrial bioenergetic contribution." (PMID 18789162, 2008). "It is apparent, therefore, that miR-17-5p does not require MYCN to exert its oncogenic activity in neuroblastoma." (PMID 18493594, 2008). "Overexpression of miRNA 17-5p-92 cluster in MYCN-not-amplified neuroblastoma cells strongly augments their in vitro and in vivo tumorigenesis." (PMID 18493594, 2008). "NAG and DDX1 are reported to be co-amplified with the MYCN gene in neuroblastoma, but amplification of DDX1 and/or NAG has no additional adverse effect on prognosis in this disease." (PMID 17601344, 2007). "Whereas neuroblastoma (NB) with MYCN amplification presents a poor prognosis, no single marker allows to reliably predict outcome in tumours without MYCN amplification." (PMID 17579628, 2007). "The resulting predictive model, achieved a predictive accuracy of 77% for neuroblastoma in stage 3 or 4 without MYCN amplification in the independent test set, using the expression values of 256 genes." (PMID 17531100, 2007). "A recent report found a correlation between LOH at 3p21 and neuroblastoma stages 1 and 4 without MYCN amplification." (PMID 17064406, 2006). "Further, these tumor promoting pathways are rarely targeted independent of MYCN deregulation as demonstrated by the absence of activating lesions in neuroblastoma tumors and cell lines without MYCN amplification." (PMID 16822308, 2006). "In favourable neuroblastomas, for example, no MYCN amplification was discovered by mass screening, and we often observed high MK plasma levels." (PMID 12771916, 2003). "The prognosis of BMP7 in neuroblastoma was independent of age and MYCN amplification." (PMID 41632777, 2026). "Moreover, multivariate analysis showed that elevated ATP13A3 expression is an independent predictor of poor prognosis in neuroblastoma, independent of MYCN amplification." (PMID 39981745, 2025). "Interestingly, treatment with cabozantinib elicited marked tumour growth delay, but not regression, in neuroblastomas arising in both Th-MYCN and Th-MYCN/ALKF1174L mice, the effect being more pronounced in the Th-MYCN mice." (PMID 40359728, 2025). "To assess whether the cytotoxic effects of Regorafenib are consistent across neuroblastoma subtypes, we examined its impact on both MYCN-amplified (SK-N-DZ) and MYCN non-amplified (SK-N-SH) cell lines." (PMID 40513779, 2025). "In addition, we have identified a small molecule compound inhibitor of the PRKCQ‐AS1 RNA and MSI2 protein interaction and have confirmed its anticancer efficacy in vitro and in a mouse model of MYCN nonamplified neuroblastoma." (PMID 40103284, 2025). "Furthermore, absence of MYCN amplification in CNS-NB FOXR2 reinforces the crucial role of FOXR2 in neuroblastoma." (PMID 40365336, 2025). "Notably, 29.6% of our neuroblastoma patients experienced spontaneous regression, a phenomenon well-documented and particularly prevalent in localized tumors without MYCN amplification." (PMID 41007141, 2025).
neuroblastoma (continued). "By contrast, using the median, low or upper quartile of PRKCQ‐AS1, MSI2 and BMX RNA expression as the cut‐off, Kaplan‐Meier survival analyses showed that high levels of PRKCQ‐AS1, MSI2 or BMX expression in MYCN‐amplified human neuroblastoma tissues did not correlate with poor patient prognosis." (PMID 40103284, 2025). "•Inactivation of the ATRX tumor suppressor in MYCN non-amplified neuroblastoma." (PMID 40286729, 2025). "Hence, JNK-dependent therapies are much more biologically relevant in MYCN-nonamplified neuroblastoma, where the JNK cascade remains intact." (PMID 41465323, 2025). "We examined whether PRKCQ‐AS1 was required for MYCN‐nonamplified neuroblastoma cell clonogenic capacity in vitro and tumor progression in vivo." (PMID 40103284, 2025). "This information may help clinical decision-making and facilitate establishing an accurate prognosis for patients with MYCN non-amplified neuroblastoma." (PMID 40286729, 2025). "In addition, it helps in decreasing the human MYCN amplified and non-amplified neuroblastoma cell lines development in vitro." (PMID 39908250, 2025). "Additionally, immunoblot analysis further revealed clear induction of cleaved PARP and cleaved caspase-3, which are present when cells undergo apoptosis, in FLIX5-treated neuroblastoma cells, irrespective of MYCN status." (PMID 40701975, 2025). "As super‐enhancers are exclusively associated with critical oncogenes and cell identity genes, we examined whether PRKCQ‐AS1 promoted MYCN‐nonamplified neuroblastoma cell proliferation." (PMID 40103284, 2025). "All two ATRX mutations showed reduced or absence of ATRX protein production in MYCN non-amplified neuroblastoma, as observed by immunohistochemistry and it may have affected the normal ATRX protein expression." (PMID 40286729, 2025). "To investigate whether iHIF2α induction also could provoke a response in neuroblastoma cells lacking MYCN-amplification we generated three clones with the same doxycycline inducible iHIF2α construct in the SH-EP2 neuroblastoma cell line." (PMID 41118218, 2025). "The strong reduction of MYCN protein levels upon activation of the HIF2α pathway in MYCN-amplified cells coupled to the drop in proliferation and expression of noradrenergic genes indicate that rather than acting as a neuroblastoma oncogene, HIF2α has potential capacity to attenuate tumor growth." (PMID 41118218, 2025). "However, based on Western blot analysis using multiple neuroblastoma cell lines, we conclude that Beta3-tubulin expression is neither correlated with MYCN expression nor with cell line sensitivity to vincristine or CBSI treatment." (PMID 40430358, 2025). "Having identified MYCN positively correlated genes, we then tested some of them, e.g., PMKs and LDHA, investigating whether they were co-localised in sEV using the doxycycline-inducible neuroblastoma cell line." (PMID 41440947, 2025). "As the understanding of how ATRX influences aggressivity in MYCN non-amplified neuroblastoma is similar to that found in MYCN amplified neuroblastoma, an important aspect of this will be to explore therapeutic vulnerabilities in patients with ATRX mutation and ATRX loss protein." (PMID 40286729, 2025). "Taken together, the data demonstrate that PRKCQ‐AS1 interacts with MSI2 to enhance BMX expression, resulting in ERK protein phosphorylation and MYCN nonamplified neuroblastoma tumorigenesis, and that PRKCQ‐AS1 and MSI2 interaction is a valid therapeutic target." (PMID 40103284, 2025). "Tumorigenic drivers of MYCN gene nonamplified neuroblastoma remain largely uncharacterized." (PMID 40103284, 2025).
neuroblastoma (continued). "Thus, it appears that neuroblastoma tumors are able to cope with hypoxic stress largely due to the combinatorial effects of HIF1α and MYCN, rather than to HIF2α expression." (PMID 41118218, 2025). "In this study, 37 tumors from MYCN non-amplified neuroblastoma patients were sequenced and the authors found two older children (NB1 and NB2) with advanced MYCN non-amplified neuroblastoma carried each one of the two following novel nonsense ATRX variants (p.Gln1670* or p.Glu1984*)." (PMID 40286729, 2025). "Multivariate survival analyses on two neuroblastoma cohorts (Kocak GSE45547; SEQC GSE62564) that incorporated MYCN amplification, patient age and tumor stage as other prognostic variables, indicated that high ATP13A3 expression is an independent prognostic marker for neuroblastoma outcome." (PMID 39981745, 2025). "This suggests that increased MCL1 activity through low-amplitude copy number gain in neuroblastoma may contribute to an aggressive phenotype in tumors without MYCN amplification, which is the strongest predictor of poor prognosis in neuroblastoma tumors." (PMID 40694850, 2025). "However, only 4h can induce apoptosis in all non-resistant neuroblastoma cells, including the vincristine-resistant MYCN-amplified cell line, indicating that 4h is more active across all biological assays tested when compared to 4k." (PMID 40430358, 2025). "However, no direct involvement of the spliceosome has been described in neuroblastoma, and thus we still do not understand the regulatory mechanisms that underpin MYCN-driven alternative splicing changes." (PMID 38049564, 2024). "Consequently SNRPD3, MYCN, and PRMT5 expression levels may be used as predictive biomarkers for PRMT5 inhibitor response, not only in neuroblastoma, but potentially other cancers." (PMID 38049564, 2024). "Our finding that neuroblastoma cells require AF1q expression for survival and tumorigenesis is further supported by the highly significant dependency score of AF1Q in MYCN amplified and non-amplified neuroblastoma cells revealed by analysis of the Depmap database." (PMID 38413795, 2024). "However, the absence of caspase-2 is not sufficient to promote tumorigenesis in the MYCN-driven neuroblastoma model or following 3-methylcholanthrene (3-MC)-induced fibrosarcoma and irradiation-driven lymphoma." (PMID 38429264, 2024). "To test this hypothesis, we incubated MYCN-amplified neuroblastoma cell lines with and without DDX1 coamplification with DM-αKG in the presence and absence of mTORC1 inhibitors." (PMID 38197697, 2024). "The findings were further confirmed by using CIBERSORTx deconvolution to quantify various immune populations based upon a MYCN non-amplified neuroblastoma scRNA-seq data, showing increased percentages of fibroblasts, B cells, myeloid cells, T cells, and pDC (plasmacytoid dendritic cells)." (PMID 38553589, 2024). "For example, the rare and aggressive MYCN-amplified RB1-wildtype subtype retinoblastoma is more therapy resistant to traditional chemotherapies, but equally chemo-sensitive to pevonedistat (a neddylation inhibitor), which is being developed as treatment for neuroblastoma." (PMID 37615761, 2024). "We propose that transcriptional subtyping may enhance precision prognosis and therapy stratification for patients with MYCN non-amplified neuroblastomas." (PMID 38553589, 2024). "Here, we investigated whether transcriptional subtyping of MYCN non-amplified neuroblastomas can identify molecular subtypes with discrete prognosis and therapeutic vulnerabilities." (PMID 38553589, 2024). "To verify the role of DDX1 as a passenger in the pathogenesis of neuroblastoma in an in vivo experimental system, we generated a transgenic zebrafish line that stably expresses human DDX1 in the peripheral sympathetic nervous system and compared those to zebrafish expressing both DDX1 and MYCN." (PMID 38197697, 2024).